FABP1 (fatty acid binding protein 1)
Diseases named in the same sentence as FABP1 in open-access papers (continued):
Sharing a sentence is not in itself a finding about the gene and the disease.
gastric cancer (11 papers, 2015 to 2025). A primary or metastatic malignant neoplasm involving the stomach. "While some studies have suggested that FABP1 is abnormally increased in advanced stages and plays a role as a biomarker in gastric cancer, it functional role and underlying molecular mechanisms in GC progression remain poorly understood." (PMID 40694956, 2025). "In gastric cancer, FABP1 expression is negatively correlated with Helicobacter pylori infection, and its progressive reduction can serve as an early diagnostic biomarker." (PMID 40717587, 2025). "Mechanically, AA inhibits the PPARγ pathway to downregulate FABP1 expression, thereby suppressing AA uptake and preventing ferroptosis of gastric cancer cells." (PMID 40694956, 2025). "For example, increased levels of FABP1 were reported in the early stage of gastric cancers, with a specificity of 95%, and in the advanced stage of cancer recurrence with a sensitivity of 67%, demonstrating a potential biomarker for the worse prognosis." (PMID 38617005, 2024). "In this study, we analyzed the single-cell sequencing data of gastric cancer and found that FABP1 was one of the most significant differentially expressed genes (DEGs) in GC tissues." (PMID 35799608, 2022). "For our analysis, we found the abnormal expression of FABP1 in early gastric cancer tissues by analyzing the data of single-cell RNA sequencing, which plays a very important role in the treatment of gastric cancer." (PMID 35799608, 2022). "PPAR signaling network (left) showed alterations of fatty acid uptake (SLC27A2/6) and transports (FABP1-6) in gastric cancers, leading to dysregulated activation of PPAR pathways, resulting in alteration of PPAR targets involved in lipid homeostasis." (PMID 26657352, 2015). "Therefore, we look forward to additional in vivo experiments with FABP1, which will ultimately benefit gastric cancer patients." (PMID 40694956, 2025). "In diagnostics, while FABP1 combined with TRIB3 can improve the sensitivity of early gastric cancer diagnosis, and FABP6 combined with CEA can enhance CRC diagnostic efficacy, the specificity of single biomarkers and expression heterogeneity across different cancer types limit clinical application." (PMID 40717587, 2025). "Finally, we identified a gene set associated with the differentiation status of gastric cancer, including AGR3, CLDN3, CLDN4, FABP1, LGALS4, PHGR1, MYH14 and S100A14." (PMID 36729271, 2023). "In our future study, we will expand the sample size to clarify these issues, and the content of FABP1 can be detected in serum and feces of patients with a confirmed diagnosis of GC, to prove that FABP1 can be used as a marker for the diagnosis of gastric cancer." (PMID 35799608, 2022). "Also included is a set of representative images of immunohistochemical staining of gastric cancer tissues showing four levels of expression of fatty acid binding protein (FABP1) and fatty acid synthase (FASN)." (PMID 28180141, 2017). "This concept is supported by the observation that a large proportion of TTF-1-positive colonic or gastric cancers also showed an immunohistochemical expression of at least one of the following markers: SATB2, CK20, FABP1, and Villin-1." (PMID 40564811, 2025). "Increased expressions of PPARA1, ACAA1, FABP1, and FABP2 were detected in SNU-478 ampullary cancer cells compared to pancreatic cancer cells (Pan1 and MIA-Pan2) and gastric cancer cells (AGS) by qPCR." (PMID 33390794, 2021). "Consistent with our transcriptomic findings, LGALS9 treatment upregulated the expression of genes involved in cholesterol metabolism (NPC2, APOA) and PPAR signalling (SCD, PLIN2, FABP1), suggesting that LGALS9‐P4HB interaction modulates lipid metabolism in gastric cancer cells." (PMID 40534096, 2025). "The results showed that the expression level of FABP1 in GC tissues was higher than that in the noncancer tissues, and the high expression rate of FABP1 in gastric cancer tissues was higher than that in noncancer tissues." (PMID 35799608, 2022).
gastric cancer (continued). "Moreover, we identified the significant DEG-FABP1 and found that FABP1 may regulate the PPAR signaling pathway, hormone-sensitive lipase (HSL)-mediated triacylglycerol hydrolysis, fat digestion, and absorption in gastric cancer progression." (PMID 35799608, 2022).
ischemia (10 papers, 2013 to 2023). A hypoperfusion of the BLOOD through an organ or tissue caused by a PATHOLOGIC CONSTRICTION or obstruction of its BLOOD VESSELS, or an absence of BLOOD CIRCULATION. "Such a spill-over of FABP1 protein may either be caused by some physiologic intravital diffusion of the highly abundant FABP1 protein or reflect an ischemia-induced artifact caused by autolytic cell damage occurring between removal of the tissue from the patient and completed tissue fixation." (PMID 35951102, 2022).
breast carcinoma (9 papers, 2008 to 2025). "FABP1 was shown to play a key role in breast cancer cells and has the potential to serve as a diagnostic marker." (PMID 27779102, 2016). "A previous study decreasing FASN and FABP1 cause inhibition of EMT in breast cancer cells." (PMID 30388870, 2018). "In addition, we found that the expression of TRIB3 were of diagnostic value for GC, while FABP1 were of diagnostic value for both GC and EGC, and as suggested by the previous research results in renal cancer and breast cancer." (PMID 34957220, 2021). "Importantly, both LCN2 and FABP1 are detectable in primary breast cancer patient samples (respectively)." (PMID 31105883, 2019). "Next, we determined the correlation between increased CD36 expression and the various FABP genes (FABP1, FABP2, FABP3, FABP4, FABP5 and FABP6) in the TCGA breast cancer cohort." (PMID 34561446, 2021). "Loss of expression of FABP4 was reported in bladder cancer while FABP1 and FABP2 are over-expressed in prostate and breast cancers." (PMID 18826602, 2008).
Hyperglycemia (8 papers, 2012 to 2021). An increased concentration of glucose in the blood. "A study reported that the common Ala/Ala94 amino acid variant in FABP1 contributed significantly to decreased hepatic glycogenolysis and less severe hyperglycemia in lipid-challenged humans." (PMID 23144966, 2012). "Additional studies have also demonstrated that the expression of the FABP1 gene in the kidneys is increased by stress, such as hyperglycemia 44, urinary protein overload 45, renal ischemia 46, and toxins 47, and such stress causes tubulointerstitial damage." (PMID 32038102, 2020).
type 1 diabetes (8 papers, 2012 to 2026). "Of note, urinary FABP1 has been linked to CKD in patients with T2DM, and it has also been reported to be a predictor of progression to microalbuminuria in patients with type 1 diabetes 28,29." (PMID 34975301, 2022).
hepatocellular adenoma (7 papers, 2011 to 2025). A benign epithelial neoplasm arising from the hepatocytes. "Loss of FABP1 expression in a hepatic tumor has been described as a feature of hepatocellular adenoma." (PMID 35951102, 2022). "In hepatocellular adenomas, efficient silencing of FABP1 can be caused by biallelic inactivation of hepatocyte nuclear factor 1α (HNF1A) which occurs in 35–40% of cases." (PMID 35951102, 2022). "In contrast, bad prognosis of hepatocellular adenoma was associated with a decrease of FABP1 and increase of hepatocyte nuclear factor 1 α (HNF-1α) and low levels of FABP1 were also found in hepatocarcinoma (HCC) patients." (PMID 32856199, 2020). "FABP1 coding for L-FABP is highly expressed in normal liver tissues compared with hepatocellular adenoma and HCC." (PMID 32098370, 2020). "For instance, the expression of FABP1 is reduced in hepatocellular adenomas (HCA)." (PMID 39744129, 2024).
liver cancer (7 papers, 2004 to 2025). An epithelial or non-epithelial malignant neoplasm that arises from the liver. "Plausibility of FABP-1 as biomarker for cancer comes from previous literature suggesting an association with colon, gastric, and liver cancers." (PMID 21251264, 2011). "For instance, Polymethyl methacrylate (PMMA) inhibits liver cancer cells by downregulating FABP1 and PPAR alpha." (PMID 41378310, 2025). "Previously it was reported that treatment of mouse primary hepatocytes with peroxisomes proliferators (including Wy14643) for 24 hours led to upregulation of 11 genes related to liver cancer (i.e. Angptl4, Bnip3, Dbi, Fabp1, Fabp2, Fasn, HifIa, Lgals3, Ly6d, Mgll, SerpineI)." (PMID 25511156, 2014). "In liver cancer, PMMA upregulated HO-1 and downregulated PPARα/FABP1, suggesting oxidative stress and lipid dysregulation." (PMID 41378310, 2025). "In addition, FABP1, HO-1, LXR-α, PPAR-alpha (PPARα), and PPARγ have been affected by MPs in liver cancer cells." (PMID 41378310, 2025). "For example, Orlistat inhibits FABP1 activity to enhance immunotherapy efficacy in HCC, BMS309403 targets FABP4 to inhibit ovarian cancer metastasis and enhance chemosensitivity, and SBFI-26 induces ferroptosis in liver cancer cells by inhibiting FABP5." (PMID 40717587, 2025). "Moreover, the expression levels of PPARα, PPARγ, FABP1, FABP4, and FABP5 were downregulated in GL22-treated xenograft tumors, indicating that GL22 exerted a significant anticancer effect against liver cancer in vivo mediated by PPAR–FABPs signaling pathway." (PMID 29880886, 2018).
hypertriglyceridemia (6 papers, 2012 to 2024). A laboratory test result indicating elevated triglyceride concentration in the blood. "The increased minor allele frequency in populations with lower TG levels suggests that the A allele of the rs2919872 of the FABP1 gene may influence FABP1 expression and protect against hypertriglyceridemia." (PMID 26439934, 2015). "Multiple regression modeling for the MetS and its components (binary) demonstrated that hypertriglyceridemia (p = 0.007) and low HDL-cholesterol (p = 0.001) were significantly correlated to serum FABP1 levels." (PMID 23144966, 2012). "Multiple regression modeling for the MetS and its components demonstrated that hypertriglyceridemia and low HDL-cholesterol were significantly correlated to serum FABP1 levels." (PMID 23144966, 2012). "Additionally, hypertriglyceridemia and low HDL-cholesterol were significantly correlated to serum FABP1 levels after adjusting for age, gender and BMI." (PMID 23144966, 2012).
nonalcoholic steatohepatitis (6 papers, 2021 to 2024). "High affinity is revealed between FABP1 and PPARa, indicating their functional interactions, which is linked to the progression of fatty liver and nonalcoholic steatohepatitis." (PMID 38464590, 2024). "This is important because the FABP1 T94A mutation, whichis seen in individuals who suffer from non-alcoholic steatohepatitis, bio-chemically actssimilar to the FABP1 null." (PMID 34612709, 2021). "Additionally, Fabp1 is increased in simple steatosis (128%), when compared to obese normal patients; however, it is under-expressed in nonalcoholic steatohepatitis, suggesting that FABP1 may function in a context-dependent manner." (PMID 35460694, 2022). "Nevertheless, the increased expression level of the Pparα–Fabp1 axis was always found in DIO mice, and the suppression of the Pparα–Fabp1 axis was considered as a treatment for nonalcoholic steatohepatitis, suggesting the potential threat of a high-BCAA diet." (PMID 36982473, 2023).
pancreatic cancer (6 papers, 2011 to 2024). "Further experimental and clinical research is required to understand the true relationship between FABP-1, pancreatic cancer, and PaC-associated DM." (PMID 21251264, 2011). "A more stringent cutoff for FABP-1 staining would change our reported associated with pancreatic cancer." (PMID 21251264, 2011). "Another example of an SL interaction predicted by the SL-scan approach is between ACADVL and FABP1 in pancreatic cancer." (PMID 37737478, 2023). "The expression of FABP1 is also positively correlated with the incidence of pancreatic cancer, especially the diabetes-related pancreatic cancer." (PMID 35799608, 2022). "However, we do feel that in this pilot study, grouping pancreatic cancer groups by the presence or absence of FABP-1 staining was reasonable, given that only one normal sample stained positive for FABP-1 and that the degree of FABP-1 expression is likely to vary between tumors." (PMID 21251264, 2011).
renal dysfunction (6 papers, 2016 to 2021). "Fatty acid-binding protein 4 (FABP4), but not FABP1 (liver-type FABP), is ectopically induced in injured glomerular endothelial cells, and urinary FABP4 (U-FABP4) level is associated with proteinuria and renal dysfunction in a general population." (PMID 33143633, 2020).
adenoma (5 papers, 2004 to 2025). A neoplasm arising from the epithelium. "The literature is variable, but loss of FABP-1 expression in colonic tissue has correlated with progression from normal colonic tissue to adenoma to carcinoma." (PMID 21251264, 2011). "Different stages of colorectal tumour development show varying levels of L-FABP expression, with a notable loss at the adenoma stage with larger adenomas exhibiting significantly decreased FABP1 staining, and immunoreactivity is significantly associated with poorly differentiated cancers." (PMID 41149452, 2025).
colorectal adenocarcinoma (5 papers, 2022 to 2025). The most common type of colorectal carcinoma. "The mechanism causing low FABP1 expression in colorectal adenocarcinomas with MSI is unclear." (PMID 35951102, 2022). "The successful analysis of more than 2000 colorectal adenocarcinomas enabled us to analyze the relationship between FABP1 expression, tumor phenotype, and molecular data in this tumor entity." (PMID 35951102, 2022). "Overexpression of FABP1 is identified in colorectal adenocarcinomas, cholangiocarcinomas, and HCC." (PMID 37835490, 2023). "However, considering that only 71% of our colorectal adenocarcinomas were FABP1 positive and the even lower frequency of FABP1 positivity in other gastrointestinal adenocarcinomas, a negative FABP1 staining cannot serve as evidence for a pulmonary origin of an adenocarcinoma in the lung." (PMID 35951102, 2022).
gastric adenocarcinoma (5 papers, 2011 to 2024). "FABP-1 is highly expressed in gastric intestinal metaplasia and a subset of gastric adenocarcinoma." (PMID 21251264, 2011). "FABP1 is highly expressed in gastric intestinal metaplasia and gastric adenocarcinoma tissues, but not or less expressed in gastric tissues." (PMID 35799608, 2022). "Fatty Acid Binding Protein 1 (FABP1) expression is high and intense in metaplasia and a fraction of gastric adenocarcinomas, although it has no relation to the carcinoma’s development, prognosis, or fatty acid synthase status." (PMID 35625633, 2022).
liver fibrosis (5 papers, 2017 to 2023). "This included genes associated with metabolism (Fabp1, Insr), genes associated with cell stress (Atf6, Ddit3, and Eif2ak3), genes associated with liver fibrosis (Hgf, Sp1, and Timp1) and genes associated with the inflammatory response (Tnf, Ptpn22, and Pparg)." (PMID 28686204, 2017).
lymph node metastasis (5 papers, 2011 to 2025). "Negative FABP-1 expression in colon cancer metastases has been associated with decreased survival, and low FABP-1 expression in colon cancer has been associated with lymph node metastasis." (PMID 21251264, 2011). "Further analysis revealed that PPARγ, a regulator of FABP1 transcription, was significantly downregulated after lymph node metastasis." (PMID 40694956, 2025). "Accordingly, IHC analysis confirmed that FABP1 expressed in DI area was higher than in T area and was significantly correlated with lymph node metastasis." (PMID 38617005, 2024). "To determine whether FABP1 attenuates LN metastasis in vivo, we constructed a footpad lymph node metastasis model using FABP1-KO MKN45 cells and the corresponding control." (PMID 40694956, 2025).
cholangiocarcinoma (4 papers, 2022 to 2025). A carcinoma that arises from the intrahepatic biliary tree (intrahepatic cholangiocarcinoma) or from the junction, or adjacent to the junction, of the right and left hepatic ducts (hilar cholangiocarcinoma). "Moreover, compared with that in other types of CCA, the expression of FABP1 was significantly elevated in hilar cholangiocarcinoma (HCCA)." (PMID 39984452, 2025).
heart failure (4 papers, 2013 to 2023). Inability of the heart to pump blood at an adequate rate to meet tissue metabolic requirements. "Since subjects with heart failure were generally excluded from the study subjects, it is unlikely that correlation of FABP1 and BNP is attributable to liver congestion by latent right ventricular failure." (PMID 24278421, 2013). "Since FABPs lack a secretory signal sequence, the presence of FABPs in serum has been considered to be a promising tissue-specific marker of tissue injury: FABP1 for liver damage, FABP2 for intestinal injury, and FABP3 for acute myocardial infarction and ongoing myocardial damage in heart failure." (PMID 24278421, 2013).
IgA nephropathy (4 papers, 2018 to 2025). "For instance, it remains undefined whether Gd-IgA1 directly binds to mesangial cell receptors to activate the PPARα–FABP1 axis, or if indirect signals (e.g., inflammatory cytokines and complement activation—hallmarks of IgA nephropathy) are required." (PMID 41425591, 2025). "Mechanistically, the downregulation of peroxisome proliferator-activated receptor α mediates the regulation of fatty acid-binding protein 1 on GPX4 and ACSL4, leading to ferroptosis and promoting the development of IgA nephropathy." (PMID 41425591, 2025).
pancreatic adenocarcinoma (4 papers, 2011 to 2023). "Increased expressions of ACAA1 (acetyl-CoA acyltransferase 1), FABP1 (fatty acid-binding protein 1), PPARA, and FABP2 genes were seen in ampullary adenocarcinomas compared to pancreatic adenocarcinomas." (PMID 33390794, 2021).
colon cancer (3 papers, 2004 to 2016). "On the contrary, one study associated low FABP-1 expression in colon cancer with increased survival." (PMID 21251264, 2011). "The significance of the downregulation of CDX1, FABP1, and MAPT in CTCs is unknown, although associations between the losses of these genes and the development and progression of colon cancer have been described." (PMID 27340863, 2016).
colorectal tumour (3 papers, 2004 to 2025). "FABP-1 gene expression has been identified as a marker of circulating colorectal tumor cells via RT-PCR." (PMID 21251264, 2011).
Gastric Diseases (3 papers, 2020 to 2022). "In conclusion, the protein expressions of TRIB3 and FABP1 gradually decreased with the gastric disease progress, and was positively correlated." (PMID 34957220, 2021). "In this study, we elucidated the protein expression of TRIB3 and FABP1 in different stages of gastric disease, and identified the correlation between their expressions." (PMID 34957220, 2021). "As far as we know, this is the first study assessing the expression trend of TRIB3 and FABP1 in the dynamic process of gastric disease development, and also the first report correlating TRIB3 with FABP1." (PMID 34957220, 2021). "Similar to FABP1, the two-stage expression pattern of CDX2 and SOX9 during the initiation and development of GC was also reported previously, suggesting that these molecules might play different roles in different stages of gastric disease progression." (PMID 34957220, 2021).
lipid metabolism disorder (3 papers, 2021 to 2025). "Mutations in FABP1 T94A may influence the uptake, transport, and metabolism of free fatty acids, thereby affecting blood lipid levels and potentially leading to lipid metabolism disorders." (PMID 38090270, 2023). "Besides, the up-regulation of Acyl-CoA synthetase long-chain family member 4 (ACSL4) and down-regulation of acetyl-coa acetyltransferase 1 (ACAT1) and fatty acid binding protein 1 (FABP-1) proteins were linked to lipid metabolism disorder." (PMID 34595163, 2021). "Dictamnine also increased intracellular lipid metabolism disorder via the down-regulation of ACAT1 and FABP-1 and up-regulation of ACSL4." (PMID 34595163, 2021).